PAK1 (p21 (RAC1) activated kinase 1)
Diseases named in the same sentence as PAK1 in open-access papers (continued):
Sharing a sentence is not in itself a finding about the gene and the disease.
lung carcinoma (continued). "Among PAKs, PAK1, PAK2, and PAK4 exhibit a higher expression level in most cancer types; PAK1 and PAK4 are the most studied and better characterized, yet PAK2 has the highest alteration frequency among all PAKs, especially in lung cancer." (PMID 36429067, 2022). "We found that the five-year mortality rates were lower in patients with PAK1-negative than in PAK1-positive EGFR mutant lung cancer." (PMID 33261184, 2020). "The roles of PAK1 and PAK2 were analyzed in detail using siRNAs in a lung carcinoma model." (PMID 31748572, 2019). "Results showed that the combination of IPA-3 plus auranofin abrogated the expression of total/phosphorylation of PAK1, PKCι, ERK 1/2, mTOR, AKT, and YAP1 in the 3 lung cancer cell lines studied HCC827 (EGFR-mutant LUAD), H23 (KRAS-mutant LUAD) and H520 (PAK1 overexpression)." (PMID 31660987, 2019). "Although OTSSP167 inhibited phosphorylated PAK1, we cannot rule out that other activators of PAK1 can intervene in lung cancer, like MLK3 and TNFα." (PMID 31660987, 2019). "Nuclear factor κB (NF-κB) subunits were also differentially phosphorylated following PAK1 inhibition in multiple squamous NSCLC cell lines and this pathway may contribute to transformation of lung cancer cells." (PMID 21653999, 2011). "Examination of CD44/PAK1/AKT activation could help to predict response to FGFR1 inhibition, and combination with AKT or PAK1 inhibitors might pave the way toward an effective therapy for FGFR1-dependent lung-cancer patients in cases of resistance to treatment." (PMID 35853934, 2022). "Nevertheless, our data showed that PAK1 might not interact with ILK in lung cancer cells even though silencing PAK1 decreased the PARVA-induced phosphorylation of ILK at Ser246." (PMID 25738875, 2015).
gastric cancer (39 papers, 2013 to 2026). A primary or metastatic malignant neoplasm involving the stomach. "In gastric cancer patients, high PAK1 expression was associated with advanced-stage tumors, distant metastasis, and reduced survival." (PMID 37190165, 2023). "Consistent with our results, overexpression of PAK1 is associated with progression, metastasis and prognosis of gastric cancer." (PMID 30971268, 2019). "Overexpression of PAK1 was observed in gastric cancer and was associated with metastasis and prognosis." (PMID 25182632, 2014). "PAK1 has been associated with gastric cancer cell migration, invasion, and hematogenous metastasis." (PMID 37190165, 2023). "Thus, the anti-neoplastic effect of GHRH antagonist, MIA-602, was found to be associated with blockage of GHRH-R-mediated PAK1/STAT3/NF-κB pathways in gastric cancers." (PMID 29983893, 2018). "Previous studies have shown that PABPC1, another member of the PABP family, plays a critical role in gastric cancer metastasis by promoting EMT through stabilizing PAK1 mRNA." (PMID 41249135, 2025). "The promoter activity and subcellular distribution of Cyclin B1 are regulated via another oncogene product, Pak1, which is overexpressed in gastric cancer." (PMID 36769170, 2023). "The silencing of PAK1 sensitizes cells to CDK4/6 inhibitor in gastric cancer cells in a PDK1-AKT1-dependent pathway." (PMID 36769170, 2023). "β‐elemene was able to enhance the radiosensitivity of gastric cancer cells by inhibiting PAK1 activation." (PMID 35500159, 2022). "The major target proteins and signaling pathways of PAK1 are introduced to regulate gastric cancer cell proliferation (MORC2, Smad2/3), migration, metastasis and invasion (ATF2/miR-132, RUFY3) and cell cycle processes (CyclinD1, Cyclin B)." (PMID 36230657, 2022). "PAK activity and the PAK-related signaling pathway was downregulated by a small-molecule drug that was designed for gastric cancer cells, and among these were: curcumin for PAK1 and GL-1196, and LC-0882, and LCH-7749944 for PAK4." (PMID 36230657, 2022). "CUR suppressed proliferation and invasion via downregulating the action of p21-activated kinase 1 (PAK1) and expression of cyclin D1 in cultured gastric cancer cells (MGC803, MKN1, SGC7901, and BGC823." (PMID 33800000, 2021). "Then, we found that the phosphorylation of MORC2 at Ser-677 (MORC2-S677A) by p21-activated kinase 1 (PAK1) promotes gastric cancer cell proliferation and tumorigenesis." (PMID 34839357, 2021). "PAK1 is localized to the cell periphery, where it contributes to gastric cancer progression and mediates oncogenic signaling." (PMID 34069055, 2021). "For example, the growth hormone-releasing hormone receptor (GHRH-R) can promote human gastric cancer via PAK1-NF-κB signaling." (PMID 32863957, 2020). "AK963, a simple urea derivative, presented a PAK1 inhibitory potency and suppressed the proliferation of gastric cancer cells by downregulation of the PAK1-NF-κB-cyclinB1 pathway." (PMID 32863957, 2020). "RUFY3 overexpression and its interaction with P21-activated kinase-1 (PAK1) leads to the formation of F-actin-enriched protrusive structures, increased epithelial-mesenchymal transition and gastric cancer cell migration." (PMID 32850870, 2020). "Previously, the potential of curcumin in regulating gastric cancer was thought attributable to downregulation of oncogenic pathways, such as PAK1 and cyclin D1 pathways." (PMID 28781948, 2017). "In summary, we confirmed that DADS reduces the expression of Rac1, Pak1 and Rock1 in gastric cancer MGC803 cells." (PMID 26871290, 2016). "More importantly, phosphorylation of MORC2 correlates positively with PAK1 expression in clinical gastric cancer." (PMID 25888627, 2015). "The 10 representative samples of gastric cancer showed a positive correlation expression between PAK1 and RUFY3." (PMID 25766321, 2015). "We also analyzed the levels of RUFY3 and PAK1 by immunohistochemistry in 40 gastric cancers specimen including metastatic tumors." (PMID 25766321, 2015).
gastric cancer (continued). "We also found that the protein expressions of RUFY3 and PAK1 positively correlate with human clinical gastric cancer samples." (PMID 25766321, 2015). "Statistical analysis revealed p-MORC2 expression positively correlated with PAK1 expression (p = 0.007) in gastric cancer tissues, which are consistent with our findings that overexpression of PAK1 upregulated p-MORC2 in gastric cell lines." (PMID 25888627, 2015). "The correlation among the expression of Rac1, Pak1 and Rock1 in gastric cancer was analyzed using Spearman's rank correlation." (PMID 23298303, 2014). "In the present study, immunohistochemistry and a tissue microarray were used in the detection of Rac1, Pak1 and Rock1 protein expression levels in gastric cancer cells, intraepithelial neoplasia and normal tissues." (PMID 23298303, 2014). "The possible mechanism of interaction between Rac1, Pak1 and Rock and other genes in gastric cancer deserves further study." (PMID 23298303, 2014). "The correlation of Rac1, Pak1 and Rock1 expression in gastric cancer was analyzed using Spearman's rank correlation, and the expression of the three groups in gastric cancer was positively correlated (r = 0.555, P < 0.05)." (PMID 23298303, 2014). "Rac1, Pak1 and Rock1 are indicators related to gastric cancer invasion and metastasis, but few reports discuss all three kinds of protein in research on gastric cancer invasion and metastasis." (PMID 23298303, 2014). "The aim of this study was to investigate the expression and clinical significance of Rac1, Pak1 and Rock1 in gastric carcinoma." (PMID 23298303, 2014). "Rac1, Pak1 and Rock1 expression in 158 cases of gastric carcinoma were investigated via immunohistochemical staining and clinical analysis." (PMID 23298303, 2014). "Positive rates of Rac1, Pak1 and Rock1 expression in normal tissue, dysplasia and gastric carcinoma show an increasing trend and are correlated with tumor lymph node metastasis and TNM stage." (PMID 23298303, 2014). "Pak1 expression levels in normal gastric tissue, intraepithelial neoplastic tissues and gastric carcinoma were 20, 35 and 60 percent, respectively, whereas Rock1 expression was 16, 28 and 58 percent, respectively." (PMID 23298303, 2014). "The positive expression rates of Rac1, Pak1 and Rock1 in normal tissue, intraepithelial neoplastic tissues and gastric carcinoma showed an increasing trend (P < 0.05)." (PMID 23298303, 2014). "In addition to these findings, increased ROS production and the activation of the FAK/AKT/p70S6K and PAK1 signaling pathways suggest a mechanism that drives apoptosis and reduces the invasiveness of gastric cancer cells." (PMID 40959699, 2025). "P21-activated kinase 1 (PAK1) is involved in gastric cancer progression." (PMID 36769170, 2023). "PAK1, a main downstream effector of small Rho GTPases, has been reported to induce the proliferation, motility, and invasion of human cancer cells, including colorectal, bladder, pancreatic, and gastric cancers." (PMID 37225681, 2023). "Pak1 regulates the mRNA and protein levels of Cyclin B1 for the promotion of progression and metastasis of gastric cancer as its knockdown resulted in the inhibition of the growth of gastric cancer cells and xenograft tumors." (PMID 36769170, 2023). "Moreover, MIA-602 was found to inhibit the growth of gastric cancer in vitro and in vivo by blocking p21-activated kinase 1 (PAK1), STAT3 and NF-kB inflammatory pathways." (PMID 36232554, 2022). "Interestingly, RUN and FYVE domain containing 3 (RUFY3), which can be up-regulated by PAK1, localizes with F-actin and formats F-actin-enriched protrusive structures to promote gastric cancer cells migration and invasion." (PMID 32863957, 2020). "Interestingly, PAK1 can also regulate cyclinB1 activity via transcription and expression enhancing through NF-KB activation in gastric cancer." (PMID 32863957, 2020).
gastric cancer (continued). "Indeed, knocking down of PAK1 significantly reduces cell adhesion, migration, and invasion of gastric cancer cells in vitro and significantly prevents tumor metastasis in vivo." (PMID 30971268, 2019). "In addition, a recent study also indicated that PAK1 promotes the invasion of gastric cancer cells by inducing the mRNA expression and activity of MMP-2." (PMID 30971268, 2019). "It will be interesting to determine if miR-3978 and PCBP1 share similar promoter architecture and whether they are both regulated by PAK1 in the context of peritoneal metastasis in gastric cancer." (PMID 29138420, 2017). "In addition, we have found that the increased expression of Rac1, Pak1 and Rock1 in primary gastric cancer is correlated with lymph node metastasis, clinical stage and poor prognosis." (PMID 26871290, 2016). "Especially for Epstein–Barr virus‐related gastric cancer, there is an inverse relation between p21 and β‐catenin, which might be mediated by PAK1‐dependent interference with Wnt signaling." (PMID 26778597, 2016). "In addition, we measured the protein levels of RUFY3 and PAK1 in 40 pairs of gastric cancer tissue samples with invasive carcinoma at pathologic TNM III and TNM IV stages through western blot." (PMID 25766321, 2015). "To examine the role of RUFY3 and its relationship with PAK1 in gastric cancer, we first investigated the protein levels of RUFY3 and PAK1 in gastric cancer cell lines (BGC-823, MKN45, AGS, MGC-803, SGC-7901 and MKN1) relative to the normal gastric epithelial cell line (GES-1) by western blot." (PMID 25766321, 2015). "The results also showed that high levels of PAK1 and RUFY3 appear to be associated with the progression and metastasis of human gastric cancer, which indicated that the expression level of RUFY3 by immunohistochemistry are correlated with PAK1, consistent with western blot results." (PMID 25766321, 2015). "Therefore, our results indicated that PAK1 regulated RUFY3-mediated gastric cancer cell migration and invasion." (PMID 25766321, 2015). "MORC2 was phosphorylated in 71% (30 of 42) of gastric cancer with overexpressed PAK1 patients." (PMID 25888627, 2015). "Furthermore, high expression of PAK1 and phosphorylation of MORC2 appear to be associated with poor prognosis of clinical gastric cancer." (PMID 25888627, 2015). "In addition, our data presented here show that high expression of phosphorylated MORC2 and PAK1 correlates postively with clinical poor prognosis of gastric cancer." (PMID 25888627, 2015). "Furthermore, we showed that PAK1 can affect RUFY3-mediated gastric cancer cell migration and invasion by regulating its expression." (PMID 25766321, 2015). "Emerging data suggest that PAK1 is overexpressed in human cancer, including gastric cancer." (PMID 25888627, 2015). "Moreover, an obvious positive correlation was observed between the protein expression of RUFY3 and PAK1 in 40 pairs of gastric cancer samples." (PMID 25766321, 2015). "Downregulation of PAK1 expression reduced gastric cancer cell migration and invasion." (PMID 25182632, 2014). "Rac1, Pak1 and Rock1 expression in gastric cancer was positively correlated (r = 0.555, P < 0.05)." (PMID 23298303, 2014). "The expression of Rac1, Pak1 and Rock1 in normal epithelium and intraepithelial neoplastic epithelium was weakly positive or positive; however, a large number of positively stained cells were heterogeneously distributed in the gastric carcinoma tissues." (PMID 23298303, 2014). "Similarly to our study, PAK1 protein overexpression and copy number gain were found in more than 40% of gastric cancer tissues, and advanced gastric cancer tissues express higher PAK1 levels than do matched noncancerous adjacent mucosa." (PMID 24236193, 2013). "However, another study reported that the PAK1 low-expression group had a unfavorable prognosis among gastric cancer patients." (PMID 24236193, 2013).
gastric cancer (continued). "In addition, PAK1 has been reported to regulate the alternative splicing of CD44 by phosphorylating PCBP115 or promote the expression of CD44 through the PAK1/ATF2/miR-132 cascade in gastric cancer." (PMID 41459112, 2026). "Indeed, ectopic expression of PAK1 facilitates the migration and invasion of gastric cancer cells." (PMID 30971268, 2019). "Therefore, based on these results, we draw a conclusion that PAK1 regulates RUFY3-mediated gastric cancer cell migration and invasion, suggesting that blocking PAK1-RUFY3 pathway might be a potential therapeutic strategy for metastasis of gastric cancer." (PMID 25766321, 2015). "Rac1, Pak1 and Rock1 expression in gastric cancer is closely related with the degree of gastric cancer lymph node metastasis and TNM stage and they play an important role in the invasion and metastasis of gastric cancer and might be key biological markers for invasion and metastasis." (PMID 23298303, 2014). "Rac1, Pak1 and Rock1 may be important biomarkers of gastric carcinoma invasion and metastasis." (PMID 23298303, 2014). "In vitro models of gastric cancer and xenografted tumors have also shown that MIA-602 can downregulate the PAK-1-mediated STAT3/NF-κB inflammatory pathway." (PMID 37370714, 2023). "Recent studies also indicate PAK1 activation by several long non-coding RNAs and miRNAs in the progression and EMT of gastric cancers." (PMID 37190165, 2023). "The correlation of MORC2 and the PAK1 pathway has also demonstrated in clinical studies showing that higher levels of PAK1 expression and phosphorylated MORC2 correlates with shorter overall survival and poor prognosis of clinical gastric cancer." (PMID 34839357, 2021). "And in gastric cancer, high phosphorylation of MORC2 is always accompany with high expression of PAK1 and involves in poor prognosis." (PMID 32863957, 2020). "Recently one research showed that in gastric cancer, RUFY3 can interact with activated P21 kinase-1 (PAK1) and promote gastric cancer metastasis." (PMID 31772661, 2019). "P21-activated kinase-1 (PAK1) interacts with RUFY3, resulting in RUFY3-induced gastric cancer cell migration." (PMID 28623323, 2017). "Using specific PAK1-shRNA interference and inhibitor IPA-3, there was a reduction in RUFY3-induced gastric cancer cell migration and invasion." (PMID 25766321, 2015). "Our data show that overexpressing PAK1 consolidated overexpressing RUFY3-induced gastric cancer cell migration and invasion, whereas the cells overexpressing GFP-RUFY3 treated with PAK1-siRNA exhibited an inhibition capacity in cell migration and invasion." (PMID 25766321, 2015). "There was a strong positive correlation between PAK1 and phosphorylation of MORC2 expression in gastric cancer samples." (PMID 25888627, 2015). "In gastric cancer samples, we showed a positive relationship between PAK1 and RUFY3, and that increased expression of RUFY3 is positively correlated with clinical gastric cancer samples." (PMID 25766321, 2015). "To better understand the correlation between them, we divided tumor samples into two groups on the basis of PAK1 amounts (cut off at the median score), and studied the differences of p-MORC2 expression with clinical gastric cancer." (PMID 25888627, 2015). "Our data are supported by the report that PAK1 is correlated with LN metastasis, lymphatic invasion, tumor size and tumor stage ([III+IV] > [I+II]) in gastric cancer." (PMID 24236193, 2013). "In gastric cancer cells, EA activates apoptosis through the FAK/AKT/PAK1 pathway." (PMID 36675019, 2023). "Indeed, in MKN45 gastric cancer cells, PAK1 silencing decreased mRNA levels and activity of MMP2 while PAK1 overexpression induced increased mRNA expression and increased activity of MMP2 leading to higher invasive properties." (PMID 34066419, 2021).
gastric cancer (continued). "To avoid the random cytotoxicity and false positive reaction of chemicals, we checked the cytotoxic effect of a group of chemicals including IPP-14 on PAK1 overexpressed pancreatic cancer cell line, MIA-Paca2, comparing to human gastric cancer cell line, MKN45." (PMID 28423593, 2017). "Furthermore, P21-activated kinase-1 (PAK1) interacts with RUFY3, and promotes RUFY3 expression and RUFY3-induced gastric cancer cell migration; inhibition of PAK1 attenuates RUFY3-induced SGC-7901 cell migration and invasion." (PMID 25766321, 2015). "Therefore, we here, established, for the first time, that there was a relationship between PAK1 and MORC2 in gastric cancer." (PMID 25888627, 2015). "The results incidated that overexpression of both p-MORC2 and PAK1 was observed in 44% (30 of 68) of gastric cancer, and neither of these two proteins presented higher expression in 23.5% (16 of 68) of tumors." (PMID 25888627, 2015). "APLN promotes the migration of gastric cancer cells 31, while in lung adenocarcinoma, apelin-13 (a 13-amino acid oligopeptide that serves as the ligand for the APLN receptor) enhances cancer cell migration via phosphorylation of the PAK1-cofilin signaling pathway." (PMID 36632453, 2023).